OR1G1 (olfactory receptor family 1 subfamily G member 1)
Description:
Odorant receptor.
Synonyms: OR17-209; OR1G2; OR17-130
Tractability: Antibody: UniProt places it where antibodies can reach, with medium confidence; UniProt predicts a signal peptide or a membrane-spanning region; its Gene Ontology location is reachable by antibodies, with medium confidence.
Gene: Protein-coding gene on chromosome 17 (3,126,610 to 3,127,551, reverse strand). Ensembl gene ENSG00000183024.
Subcellular location: Cell membrane
Pathways (Reactome):
Sensory Perception: Expression and translocation of olfactory receptors
Gene Ontology:
Molecular function: G protein-coupled olfactory receptor activity; olfactory receptor activity; G protein-coupled receptor activity; signaling receptor activity
Biological process: adenylate cyclase-activating G protein-coupled receptor signaling pathway; signal transduction; detection of chemical stimulus involved in sensory perception of smell; G protein-coupled receptor signaling pathway; sensory perception of chemical stimulus
Cellular component: plasma membrane; membrane
Genetic constraint (gnomAD): Loss-of-function variants: 1 observed, 1.08 expected, observed/expected ratio (o/e) 0.93, 90% interval 0.25 to 1.88. That is too few expected variants to judge how well the gene tolerates losing a copy. Missense variants: 347 observed, 396.14 expected, observed/expected ratio (o/e) 0.88, 90% interval 0.8 to 0.96. Synonymous variants: 145 observed, 158.71 expected, observed/expected ratio (o/e) 0.91, 90% interval 0.8 to 1.05.
Homologues: Orthologues: chimpanzee OR1G1 (96% identical). Paralogues in human: OR7A5 (58% identical), OR7A10 (57% identical), OR7A17 (56% identical), OR7C1 (56% identical), OR1F1 (55% identical), OR1E1 (55% identical), OR1I1 (55% identical), OR7D2 (55% identical), OR1E2 (54% identical), OR7D4 (54% identical), OR7E24 (54% identical), OR7G3 (54% identical), and 116 more.
Diseases named in the same sentence as OR1G1 in open-access papers:
OR1G1 is named in the same sentence as 4 diseases in open-access papers, as found by Europe PMC text mining. Sharing a sentence is not in itself a finding about the gene and the disease. The quoted sentences say what the papers report.
asthma (1 paper, 2024). "Thus, the study underscores the potential utility of targeting lung epithelial OR51B5 and OR1G1 as drug targets for odorant-induced asthma with non-type 2 inflammation." (PMID 39538061, 2024).
leukemia (1 paper, 2024). A malignant (clonal) hematologic disorder, involving hematopoietic stem cells and characterized by the presence of primitive or atypical myeloid or lymphoid cells in the bone marrow and the blood. "OR51B5 and OR1G1 have been previously found in various cell types; for example, OR51B5 in keratinocytes, K562 leukemia cells, while OR1G1 was detected in Dermal papilla cells (DPCs) and primary iliac Enterochromaffin cells." (PMID 39538061, 2024).
OR1G1 also shares sentences with these, for which no sentence is quoted: Alzheimer disease (1 paper); neurological diseases (1).